INS (insulin)
Diseases named in the same sentence as INS in open-access papers (continued):
Sharing a sentence is not in itself a finding about the gene and the disease.
Hypoglycemia (continued). "In a prototypical fashion, glucagon is released upon hypoglycemia to elevate glucose by acting on the liver while elevated glucose induces the secretion of insulin which leads to sugar uptake by peripheral tissues." (PMID 37645413, 2023). "Patients who underwent changes in their oral hypoglycemic medication or insulin dosage or reported significant changes in their lifestyle were also found to have a higher likelihood of experiencing severe hypoglycemia." (PMID 38169925, 2023). "Drug-induced hypoglycaemia is frequently experienced by diabetic patients, particularly those who are using insulin analogues and sulfonylureas, compared to other classes of antidiabetic medications." (PMID 37476614, 2023). "Medical management of sequalae of insulinomas consists of treatment of hypoglycemia, suppression of insulin blood levels, and dietary measures." (PMID 38260191, 2023). "It is worth highlighting that all the guidelines that proposed insulin therapy considered the importance of education in its use and/or the detection of hypoglycemia." (PMID 37126189, 2023). "Simultaneously, food intake before exercise and suspending the insulin pump during exercise were associated with lower TBR in the 24 h after the exercise, protecting against hypoglycemia." (PMID 36964201, 2023). "In fact, hypoglycemia, dehydration, caffeine withdrawal, free fatty acids, sympathetic nervous system activation, hypothalamic dysfunction, insulin, and several other hormonal factors have been considered potential triggers for headaches." (PMID 36904225, 2023). "It turned out that he injected himself with too much insulin, in order to induce hypoglycemia and receive extra food." (PMID 37033248, 2023). "Results from the CGM-substudy supported the results from the main trial, but the relative rate reduction for hypoglycemia during treatment with insulin degludec was even higher." (PMID 38089060, 2023). "Low body fat and hypoglycemia have been found to counteract the metabolic action of insulin and are considered to be a factor contributing to the development of IR and associated metabolic abnormalities." (PMID 37715242, 2023). "The impact of tirzepatide on the glycaemic profile has been reported as fasting glycaemia, post-prandial glycaemia, HbA1c and insulin sensitivity as well as hypoglycaemia." (PMID 37209215, 2023). "Hypoglycaemia and weight gain are two of the most common and clinically significant side effects of combining sulphonylureas with insulin." (PMID 37132569, 2023). "It will be important for future studies to further probe this relationship, but based on the current data, a progressive decline in hepatic glycogen would be expected to further diminish the hormonal and hepatic responses to insulin-induced hypoglycemia." (PMID 37166980, 2023). "The effect of fasting on glucose metabolism has been studied for many years, yet very little is known about how it impacts the CRR to insulin-induced hypoglycemia." (PMID 37166980, 2023). "Studies showed that the insulin-independent mechanism is another reason for fasting hypoglycemia in GDH-HI." (PMID 36721237, 2023). "Nocturnal hypoglycemia (NH) is a potentially dangerous and underestimated complication of insulin therapy." (PMID 37888065, 2023). "In terms of hypoglycaemic events per week, the mean number of hypoglycaemias per week before insulin pump therapy was 4.8 ± 3 episodes per week, with 6.5 ± 3.2 episodes per week in children." (PMID 37185052, 2023). "This is particularlyemphasized by the MARD for the group of subjects with type 1 diabeteson intensive insulin therapy with the glucose values below 3.9 mmol/L(i.e., hypoglycemia)." (PMID 36877178, 2023). "It was reported that IGF2, similar to insulin, can promote hypoglycemia by enhancing glucose uptake by skeletal muscle and inhibiting glucose release from the liver." (PMID 37152930, 2023).
Hypoglycemia (continued). "Diazoxide is a drug used to treat hypoglycemia, which acts by opening ATP-sensitive potassium channels on pancreatic β-cells to potently inhibit insulin release, thus increasing blood glucose levels." (PMID 36834669, 2023). "Insulin autoimmune syndrome (IAS) is a rare endocrine disorder characterized by recurrent episodes of severe hypoglycemia, markedly elevated serum insulin, and positive insulin autoantibodies." (PMID 36844104, 2023). "Various other studies have examined the contribution of the insulin pump to glycaemic control, the reduction of insulin requirements and the reduction in terms of hypoglycaemia frequency." (PMID 37185052, 2023). "Patients are supposed to log their FBG readings and episodes of hypoglycemia events or administered insulin doses." (PMID 36749650, 2023). "The occurrence of hypoglycemia (31%), weight gain (26%), and the fear of needles (22%) were commonly reported barriers during the use of insulin injections." (PMID 37240580, 2023). "The simultaneous association of the two diseases leads to frequent episodes of hypoglycemia due to the decrease in gluconeogenesis and the increased sensitivity to insulin." (PMID 36983604, 2023). "Conversely, acute or chronic experimental hypoxemia or hypoglycemia in otherwise uncompromised fetal sheep reduced insulin secretion." (PMID 37727657, 2023). "Older studies induced hypoglycemia with intravenous regular human insulin in contrast to subcutaneous rapid insulin analogs in our trial." (PMID 37334295, 2023). "For instance, one clinical trial showed that plasma ghrelin falls both following a short insulin infusion leading to hypoglycemia and following a short insulin infusion plus dextrose infusion to maintain euglycemia." (PMID 37334290, 2023). "For the same dose of NaCN (25 μg/kg), the CSN activity was significantly augmented during insulin‐induced hypoglycaemia compared to euglycaemia (P = 0.0001; for the maximum peak response)." (PMID 36459572, 2023). "Four of these individuals reported over-correcting with insulin resulting in hypoglycaemia (quote 7)." (PMID 37864225, 2023). "Yet, those treatments are time- and effort-consuming and anti-diabetic medications have potential life-threatening adverse effects such as maternal hypoglycemia following insulin or glibenclamide use." (PMID 37049473, 2023). "This is particularly relevant for patients using insulin or insulin secretagogues, as they can experience delayed nocturnal or fasting hypoglycemia after evening alcohol consumption." (PMID 37107279, 2023). "The presence of hypoglycemia while the patient was receiving IV dextrose at a high GIR as well as an inappropriately incomplete suppression of insulin point to a functional hyperinsulinemic state, likely exacerbated by overall illness and malnutrition." (PMID 37927489, 2023). "For this reason, many guidelines have been designed to help people with T1DM adjust their insulin dose and carbohydrate (CHO) intake to reduce their risk of hypoglycemia." (PMID 37942293, 2023). "In summary, the glucose-stimulated insulin secretion of the β-cells increases, giving rise to hyperinsulinemic hypoglycemia." (PMID 37371827, 2023). "In this case, blood tests showed hypoglycemia and excessive insulin secretion, leading to insulinoma and reactive hypoglycemia as differential diagnoses." (PMID 38868726, 2023). "Some individuals would entirely avoid giving insulin due to the perceived hassle of having to manage hypoglycaemia whilst in social spaces (quote 8)." (PMID 37864225, 2023). "This was reflected in a mean 8 unit reduction in insulin dose and a reduction of HbA1c at 24 months, with improved hypoglycaemia awareness and reduction of severe hypoglycaemia episodes." (PMID 36538062, 2023). "One straightforward way to avoid hypoglycemia during fasting is a change in the timing and/or dose of insulin." (PMID 37166980, 2023).
Hypoglycemia (continued). "Following RYGB, nutrient-induced peak concentrations of GLP-1, insulin and C-peptide are greater, while HbA1c is less in individuals with post-bariatric surgery hypoglycaemia." (PMID 37439960, 2023). "In the insulin treatment group, the number and severity of cases of hypoglycemia, as well as weight, significantly increased." (PMID 37373620, 2023). "In CHI, faulty KATP channel genes that reduce or abolish functional channels in the β-cell membranes uncouple blood glucose from insulin secretion, leading to inappropriate insulin secretion despite life-threatening hypoglycemia." (PMID 37056678, 2023). "In this context, hypoglycemia was the main limiting factor of first-generation antidiabetic agents, such as sulfonylureas and insulin." (PMID 37700155, 2023). "The number of hypoglycemia episodes was similar between insulin dosing algorithms for the high protein-fat meals; hypoglycemic events were considerably higher for the modified FPU in the normal protein-fat meal (p = 0.042)." (PMID 37845717, 2023). "She had a 72-hour prolonged fast, which was terminated when hypoglycemia (BG = 2.2 mmol/L) ensued after 12 hours, with elevated serum insulin and C-peptide." (PMID 38116164, 2023). "Glycated haemoglobin (HbA1c –primary outcome), time in range (blood glucose: 3.5–10.0 mmol/L), frequency of hypoglycaemia (<3.5 mmol/L), total daily insulin, and quality of life were assessed before and after the control and intervention periods." (PMID 37432920, 2023). "Patients who had hypoglycemia on the day of hemodialysis on CGM results were advised to take OAD or insulin after an afternoon meal." (PMID 37089609, 2023). "One of the reasons for the high proportion of severe hypoglycemia in this study was that most of the subjects were already taking insulin (60,8%), which was 62.7% of them used basal-bolus." (PMID 37758787, 2023). "The occurrence of hypoglycemia (31%), weight gain (26%), and needle phobia (22%) were frequently cited as obstacles to insulin injection use." (PMID 37240580, 2023). "In aerobic exercise, a basal insulin rate reduction of 50–80% has been shown to potentially prevent hypoglycemia during and post-exercise." (PMID 38068755, 2023). "Initial laboratory evaluations revealed hypoglycemia with inappropriately high insulin levels, moderate ketosis, and mildly elevated AST/ALT levels." (PMID 37181921, 2023). "Transitional HI in normal newborns is a hypoketotic form of hypoglycemia due to persistence of fetal insulin regulation by pancreatic beta-cells." (PMID 36969273, 2023). "Insulin-induced recurrent hypoglycemia in streptozotocin-induced diabetic rats leads to an increase in malondialdehyde levels and a reduction in aconitase activity, which are indicators of oxidative stress in brain mitochondria." (PMID 37298308, 2023). "Acute administration of insulin and/or insulin‐induced hypoglycaemia leads to sustained increase in CSN activity with comparable changes in respiratory and cardiovascular parameters." (PMID 36459572, 2023). "Newer generation antidiabetic therapies are reported to have a lower incidence of drug-induced hypoglycemia than standard insulin replacement therapy and are therefore preferentially used in current medical practice." (PMID 37372995, 2023). "High mortality of the RT2;B6 model, resulting from hypoglycemia due to insulin-producing PanNET cells, has posed challenges for in-depth studies into metastatic progression." (PMID 37843277, 2023). "The secondary outcome included insulin dosage to achieve glycemic control and the incidence of hypoglycemia during hospitalization." (PMID 38008775, 2023). "For example, insulin can incur life-threatening hypoglycemia despite co-administration of glucose, particularly in CKD patients who have reduced renal clearance of infused insulin and compromised gluconeogenic pathways." (PMID 37016309, 2023).
Hypoglycemia (continued). "These mice preferentially utilize lipids relative to carbohydrates during periods of rest/fasting, display mild hypoglycemia during fasting, are resistant to diabetes despite significantly elevated adiposity, and have a greater response to exogenous insulin." (PMID 37667562, 2023). "Bolus administration of insulin (12.5–25–50–100 μU) into the common carotid artery elicited significant hypoglycaemia (P = 0.0001) and significant changes in arterial pH (P = 0.0457) and PCO2 (PaCO2; P = 0.0097)." (PMID 36459572, 2023). "Second-generation basal insulin (BI) analogues (Gla-300, degludec) have comparable glycemic efficacy with less hypoglycemia compared to first generation BI analogues." (PMID 36624650, 2023). "It is worth noting that glucagon is the counterregulatory hormone to insulin, induced by fasting or hypoglycemia to raise blood glucose through action mediated in the liver." (PMID 37051358, 2023). "Human and rodent response to circadian disruption spans from development of hypoglycemia to hyperglycemia and insulin resistance." (PMID 37727248, 2023). "Congenital hyperinsulinism (CHI) is a rare condition characteristed by severe and often refractory hypoglycaemia in infants and young children, due to inappropriate excess insulin secretion from pancreatic β-cells." (PMID 38027197, 2023). "Experimentally, CK-BB enzyme activity was found to increase during insulin-induced hypoglycemia and showed a positive correlation with insulin dose." (PMID 38026658, 2023). "Hypoglycemia (2.6 mmol/L) raised the suspicion of insulinoma, although the blood insulin level of 10mIU/L was just below the normal reference range (11.6–29.0)." (PMID 38260191, 2023). "In the present case study, shortly after taking sulfhydryl-containing medicine due to drug-induced liver injury, case 3 developed frequent hypoglycemia with inappropriately high insulin levels (>1000 mU/L)." (PMID 36459334, 2023). "Insulin is administrated into systemic circulation directly by injections, generating peripheral hyperinsulinemia, which leads to hypoglycemia, cancer, atherosclerosis, and peripheral hypertension." (PMID 37781530, 2023). "Insulin use, in comparison to tablet Empagliflozin, results in up to 4-hour FDG administration delay, induces skeletal muscle uptake, and poses a risk of hypoglycemia in patients." (PMID 37854083, 2023). "In a small non-randomized study, 89 patients with T2D and CKD (mean eGFR 34.1 ± 11.5 mL/min/1.73 m2), who were poorly controlled or experienced frequent hypoglycemia on oral ADs or NPH insulin, were prescribed glargine U100 at bedtime." (PMID 37468901, 2023). "Blood glucose monitoring intraoperatively, with insulin or other medication adjustments as needed is essential, all while preventing the occurrence of hypoglycemia." (PMID 38144367, 2023). "Taken together, the model had high discriminability and predictive value for hypoglycemia in T2DM patients after intensive insulin therapy." (PMID 38223574, 2023). "Insulin treatment was stopped after 3 weeks, following complaints of fasting hypoglycemia, and subsequently whole‐day hypoglycemias." (PMID 36398453, 2023). "Previous study has shown that about 37% of patients receiving insulin therapy developed hypoglycemia, and about 2.3% of patients with T2D had severe hypoglycemia annually." (PMID 37242426, 2023). "Height, systolic blood pressure, time in hypoglycemia, and total daily and basal/total insulin dose were positively correlated to sweat response, while low-density lipoprotein, and HbA1c were negatively correlated with sweat response (p values < 0.05)." (PMID 37682387, 2023). "Once plasma insulin (antigen) increases to a certain level, the insulin-autoantibody complex becomes unstable and abruptly disintegrates, leading to postprandial hypoglycemia." (PMID 36844104, 2023). "The main side effect of insulin therapy is hypoglycemia, which occurs when the insulin action exceeds the physiological need." (PMID 38089060, 2023).
Hypoglycemia (continued). "On the other hand, it is known that CSII is associated with a reduction in total daily insulin (TDD), which can positively affect body weight, as well as the reduction in hypoglycemia and this is especially true in the era of AIDs." (PMID 38068733, 2023). "The strengths of this study include the valuable insight it provides into the level of knowledge about hypoglycemia and its management among insulin-requiring diabetic patients in Al Ahsa, Saudi Arabia." (PMID 37859676, 2023). "The potential adverse reactions of high-dose insulin are hypoglycemia and hypokalemia, which are rare in practice because of concomitant glucose and potassium supplementation." (PMID 37058027, 2023). "Insulin administration requires effective doctor–patient communication for careful monitoring of hypoglycemia, pneumonia, acute exacerbation of COPD, and respiratory failure with immediate and appropriate disposal." (PMID 37242426, 2023). "Incidence of hypoglycemia (<70 mg/dL) while on insulin infusion was significantly higher for those with euglycemic DKA (18.2 vs 4.8%, P = 0.02); incidence of hypokalemia (<3.3 mmol/L) was 27.3 vs 19.1% (P = 0.23)." (PMID 38165186, 2023). "As well, the extended hypoglycemia recorded during the ITT challenge suggested an elevated insulin sensitizing effect." (PMID 36829899, 2023). "According to the data, insulin-related hypoglycemia results in about 98 thousand emergency room visits annually, as well as 30.000 hospitalizations in the US." (PMID 36974247, 2023). "The topics most often discussed by HCPs included blood glucose monitoring before, during, and after exercise; insulin adjustments for exercise; and preventing hypoglycemia with exercise." (PMID 40303245, 2023). "Oral insulin administration has several benefits such as fast hepatic insulin delivery, avoidance of peripheral hyperinsulinemia, weight gain, hypoglycemia, and improved patient compliance." (PMID 37781530, 2023). "Previously, using glucose clamp techniques, our research group has demonstrated that overweight and insulin resistant individuals have augmented responses of the cortisol axis to hypoglycemia and impaired suppression of glucagon during hyperglycemia." (PMID 37400734, 2023). "Continuous glucose monitor use would be useful in future studies to better capture rates of hypoglycemia among insulin-treated patients placed on GLP-1 RAs." (PMID 37589043, 2023). "The combination of DE-71 effects - exaggerated fasting hypoglycemia, glucose intolerance and incomplete glucose clearance/utilization in response to insulin challenge demonstrates the complex actions of PBDEs on glucose homeostasis in males." (PMID 37008952, 2023). "As regards hypoglycemic episodes, the insulin degludec group showed a significantly lower frequency of hypoglycemia and severe hypoglycemia at the end of the study than baseline (p = 0.03 and p = 0.017, respectively)." (PMID 36800034, 2023). "Previous work has demonstrated that the ingestion of a mixed meal prior to insulin-induced hypoglycemia also increases glucagon secretion, most likely due to hyperaminoacidemia." (PMID 37166980, 2023). "The Tayside Insulin Management education program also showed reduced rates of severe hypoglycemia, reduction in HbA1c, and a 25% improvement in awareness after 6-month of the program." (PMID 37942482, 2023). "The aim was to induce hypoglycaemia at the time of maximum glucose-lowering effect for both insulin products to facilitate appropriate comparison." (PMID 37308751, 2023). "Glucose-sensitive automated insulin delivery systems, predictive insulin pump therapy for low glucose management, and hybrid closed-loop systems have resulted in improvements in glycemic control and reduced exposure to hypoglycemia." (PMID 37569354, 2023). "Islet transplantation is an effective treatment that reduces severe hypoglycaemia, re-establishes hypoglycaemia awareness, stabilises glycaemic control and can provide insulin independence." (PMID 36899932, 2023).